ENSG00000276057
Gene: Miscellaneous RNA gene on chromosome 22 (30,971,296 to 30,971,382, forward strand). Ensembl gene ENSG00000276057.
Gene Ontology:
Biological process: regulation of eye photoreceptor cell development